CENPQ (centromere protein Q)
Description:
Component of the CENPA-CAD (nucleosome distal) complex, a complex recruited to centromeres which is involved in assembly of kinetochore proteins, mitotic progression and chromosome segregation. May be involved in incorporation of newly synthesized CENPA into centromeres via its interaction with the CENPA-NAC complex. Plays an important role in chromosome congression and in the recruitment of CENP-O complex (which comprises CENPO, CENPP, CENPQ and CENPU), CENPE and PLK1 to the kinetochores.
Synonyms: CENP-Q; C6orf139; FLJ10545
Tractability: PROTAC: ubiquitination databases record sites on it.
Gene: Protein-coding gene on chromosome 6 (49,463,335 to 49,495,815, forward strand). Ensembl gene ENSG00000031691.
Subcellular location: Nucleus; Chromosome, centromere
Subcellular location (Human Protein Atlas): Nucleoplasm
Pathways (Reactome):
Cell Cycle: Amplification of signal from unattached kinetochores via a MAD2 inhibitory signal; Deposition of new CENPA-containing nucleosomes at the centromere; EML4 and NUDC in mitotic spindle formation; Mitotic Prometaphase; Resolution of Sister Chromatid Cohesion; Separation of Sister Chromatids
Signal Transduction: RHO GTPases Activate Formins
Gene Ontology:
Molecular function: protein binding
Biological process: metaphase chromosome alignment; positive regulation of protein localization to kinetochore; chromosome segregation
Cellular component: inner kinetochore; nucleoplasm; cytosol; nucleus; chromosome, centromeric region
Genetic constraint (gnomAD): Loss-of-function variants: 8 observed, 13.88 expected, observed/expected ratio (o/e) 0.58, 90% interval 0.34 to 1.04. The upper end of that interval is the gene's LOEUF score, 1.04, which puts it in group 4 of 6, group 1 being the genes least tolerant of losing a copy. Missense variants: 136 observed, 149.77 expected, observed/expected ratio (o/e) 0.91, 90% interval 0.79 to 1.05. Synonymous variants: 42 observed, 50.61 expected, observed/expected ratio (o/e) 0.83, 90% interval 0.65 to 1.07.
Homologues: Orthologues: macaque CENPQ (91% identical), chimpanzee CENPQ (87% identical), dog CENPQ (74% identical), pig CENPQ (72% identical), guinea pig CENPQ (68% identical), mouse Cenpq (65% identical), rat Cenpq (61% identical).
Diseases named in the same sentence as CENPQ in open-access papers:
CENPQ is named in the same sentence as 7 diseases in open-access papers, as found by Europe PMC text mining. Sharing a sentence is not in itself a finding about the gene and the disease. The quoted sentences say what the papers report.
autoimmune disease (1 paper, 2022). A disorder resulting from loss of function or tissue destruction of an organ or multiple organs, arising from humoral or cellular immune responses of the individual to their own tissue constituents. "An example of this is CENPQ, a centromere protein involved in autoimmune disease and mitosis progression, whose species-specific DEU is driven by a genetic change in the primate splice sites." (PMID 35840341, 2022).
tumor (5 papers, 2018 to 2025). "Interestingly, the tumor with the highest expression of CENPQ was mutated at the highly conserved position 9 of the CTCF motif, while the other two tumors were mutated at position 2 of the CTCF motif." (PMID 29670109, 2018). "When comparing tumor tissues to standard controls, a substantial upregulation of four genes was observed: CENPQ, YAE1, FANCF, and POC5." (PMID 41502527, 2025). "We found that the mRNA levels of 4 out of 15 centromere proteins (CENPL, CENPQ, CENPR, and CENPU) were significantly higher in HCC than in normal tissues, and their mRNA levels were associated with the tumor stages (p values < 0.01)." (PMID 34457090, 2021). "Out of the four CBS hotspots we examined, three of them were associated with nominally significant expression changes of neighboring genes (CENPQ, KCNQ5, and SPG20), and these associations were validated in an independent tumor cohort." (PMID 29670109, 2018). "The analysis showed that high mRNA levels of CENPL, CENPQ, CENPR, and CENPU were significantly correlated with tumor stages (p < 0.01)." (PMID 34457090, 2021). "Then, we selected 4 CENPs (CENPL, CENPQ, CENPR, and CENPU) with high expression in HCC as shown in both the Oncomine and GEPIA databases to further analyze the relationship between mRNA levels and tumor stages." (PMID 34457090, 2021).
CENPQ also shares sentences with these, for which no sentence is quoted: adenocarcinoma (1 paper); breast carcinoma (1); colorectal adenocarcinoma (1); esophageal cancer (1); Stroke (1).